FGFR3 (fibroblast growth factor receptor 3)
Diseases named in the same sentence as FGFR3 in open-access papers (continued):
Sharing a sentence is not in itself a finding about the gene and the disease.
bladder cancer (continued). "Targeting FGFR3 mutations with erdafitinib has been approved for advanced bladder cancer with an overall response of 40%." (PMID 35784457, 2022). "Bladder cancer has a high mutational burden, and fibroblast growth factor receptor 3 gene (FGFR3) is one of the most frequently mutated genes in bladder cancer." (PMID 35384983, 2022). "Fundamental mechanisms of the immunobiological process associated with FGFR3 need to be further explored to throw light on the treatment of bladder cancer." (PMID 35991125, 2022). "As some studies have discovered various FGFR mutations in up to 60% of all urothelial carcinoma and FGFR3 mutations in 15% of metastatic urothelial carcinoma, new bladder cancer therapies have begun targeting patients with FGFR‐specific mutations." (PMID 34114376, 2021). "Recent bladder cancer studies have shown that genetic mutations in bladder epithelial cells frequently occur in FGFR3, PIK3CA, and RAS (all associated with RAS signaling networks)." (PMID 34234808, 2021). "Genomic analysis of bladder cancer has identified frequent alterations of FGFRs, including overexpression and mutations of FGFR3 that activate the receptor via ligand-independent dimerization." (PMID 34984415, 2021). "It has been reported that FGFR3 has a common mutational gene in bladder cancer and its mutation was associated with a favorable BC prognosis, which was in accordance with the low UPR-related risk score in the mutational type of EGFR3." (PMID 35004850, 2021). "A phase III clinical trial is testing this agent in the adjuvant setting following surgery in advanced bladder cancer with susceptible FGFR3 genetic alterations (ClinicalTrials.gov Identifier, NCT04197986)." (PMID 34638374, 2021). "This modeling study not only quantifies the influence of the FGFR3 mutation on bladder cancer growth; it also predicts various outcomes for RTK and ICI mono- and combination therapy." (PMID 34984415, 2021). "The most frequently mutated genes in the chemo-naïve samples were well-established bladder cancer–associated genes: FGFR3 (70%), KMD6A (47%), PIK3CA (38%), KMT2D (26%), and ARID1A (23%)." (PMID 34934968, 2021). "From voided urine samples, initially, the three methods (CYTO, LOH, and FGFR3) were assessed individually for their diagnostic accuracy to detect bladder cancer cells in urine." (PMID 34884669, 2021). "Among twenty patients with FGFR3-mutated bladder cancer, two demonstrated stable responses to AZD4547." (PMID 34639155, 2021). "Among these, NOTCH1, CCND1, CD44, MMP7, TGFR2, and FGFR3 are involved in bladder cancer signaling pathways or are associated with the development of bladder carcinoma." (PMID 33535616, 2021). "In this review, we summarize recent findings on FGF/FGFR signaling, activating mutations, and other alterations of FGFR3 in bladder cancer." (PMID 34638374, 2021). "Clonal shifts are well documented during localized bladder cancer invasion into the muscle-bed; for example, the common loss of FGFR3 hotspot mutations." (PMID 33420073, 2021). "FGFR3 mutations have been found to be particularly frequent in bladder cancer (20%), where the results showed an association with early stage, low grade, and better survival." (PMID 33704917, 2021). "In bladder cancer, FGFR3 is frequently dysregulated, mainly caused by genetic alterations such as activating mutations or gene fusions." (PMID 34768978, 2021).
bladder cancer (continued). "The most frequent mutation in FGFRs is the FGFR3 S249C, which is also located in the ligand-binding region, and known as a hotspot mutation in bladder cancer." (PMID 34272467, 2021). "In a tobacco carcinogen OH-BBN-induced mouse bladder cancer model, the FGFR3-S249C mutation led to enhanced bladder tumorigenesis but also suppressed the acute inflammatory response at an early tumor initiation stage." (PMID 34638374, 2021). "Studies for AZD4547 and BGJ389 revealed that patients with FGFR1 amplification (non-small cell lung cancer) or bearing FGFR3 mutations (bladder cancer) displayed a partial response to the therapy." (PMID 33898310, 2021). "The most common FGFR3 alterations in advanced bladder cancer are activating missense mutations and in-frame FGFR3-TACC3 fusions." (PMID 34638374, 2021). "Mutation of the FGFR3 gene is beneficial in the development and progression of bladder cancer since it changes a key gene that regulates the cell–cell and cell–matrix adhesion properties of urothelial cells." (PMID 34178679, 2021). "Consistent with previous studies, in the present study, FGFR3 mutation was found in 2 cell lines (29%) among seven bladder cancer cell lines." (PMID 32325639, 2020). "The fibroblast growth factor receptor 3 (FGFR3) gene has long been associated with bladder cancer oncogenesis and recently become a therapeutic target." (PMID 33224141, 2020). "The mutation hotspots analyzed in our study should cover more than 90% of bladder-cancer-relevant gain-of-function mutations of the FGFR3 gene and ~80% of TERT promoter mutations, respectively." (PMID 32213857, 2020). "Studies have shown that dysfunction in FGFR3 or mutations of FGFR3 are highly associated with multiple cancers, such as multiple myeloma, bladder cancer, breast cancer, and colorectal cancer." (PMID 33381388, 2020). "FGFR3 expression level and mutation status were shown to be determinants of bladder carcinoma progression." (PMID 33238591, 2020). "Activating FGFR3 mutations were frequently observed in bladder cancer, leading to morphological transformation and cell proliferation." (PMID 33335285, 2020). "Mutations or translocations of FGFR3 are instead implicated in cervical cancer, multiple myeloma, and bladder cancer." (PMID 33352931, 2020). "The increased or mutated expression in FGFR3 leads to malignant progression in bladder cancer, colon cancer, and multiple myeloma." (PMID 33381388, 2020). "Chimeric protein of FGFR3-BAI associated protein 2 like 1 (BAIAP2L1) in bladder carcinoma is example of this rearrangement." (PMID 31007851, 2019). "Overexpression of FGFR3 has been associated with several types of cancer, including multiple myeloma, bladder cancer, non-small cell lung cancer, oral cancers, and oropharyngeal squamous cell carcinoma." (PMID 31619201, 2019). "Previous studies have highlighted FGFR3 mutations in an array of malignancies, including breast cancer, bladder cancer, prostate cancer, and squamous non-small cell lung carcinoma (sqNSCLC)." (PMID 31565188, 2019). "FGFR3 mutations are strongly associated with low-grade and low stage bladder cancer, with lower frequency of recurrence." (PMID 31369573, 2019). "For instance, MC1R polymorphism affects BRAF mutant melanoma, a JAK2 germline polymorphism affects JAK2 V617F mutant myeloproliferative neoplasms, and TACC3 polymorphism affects FGFR3 mutant bladder cancer." (PMID 31369573, 2019). "Silencing or inhibition of mutant FGFR3 in bladder cancer cell lines is associated with decreased malignant potential, confirming its important driver role in UC." (PMID 30952872, 2019).
bladder cancer (continued). "Firstly, we confirmed that mutant FGFR3 causes an increase in ETV5 expression in bladder cancer cells by using the two cell lines with the commonest FGFR3 mutation, 97-7 and UMUC14." (PMID 30952872, 2019). "Mutations in FGFR3 have been reported in bladder cancer to be associated with a less-aggressive disease, lower-stage tumors, and improved prognosis, consistent with the data from our study." (PMID 31619281, 2019). "The enhancement of the FGFR2 pathway would lead to urothelium proliferation and FGFR1, as well as FGFR3 gene amplification can cause urinary bladder carcinoma." (PMID 31878098, 2019). "We also demonstrate that ETV5 is a key downstream mediator of the oncogenic effects of mutant FGFR3, as its knockdown in FGFR3-mutant bladder cancer cell lines is associated with reduced proliferation and anchorage-independent growth." (PMID 30952872, 2019). "Mutations, translocations and amplification of the FGFR3 gene that lead to increased expression and receptor activity have been found in a variety of tumor types, but most frequently in bladder cancer." (PMID 29423038, 2018). "Promising results were recently reported for four out of the five patients with FGFR3‐mutated bladder cancers enrolled in a phase I clinical trial of the pan‐FGFR kinase inhibitor BGJ398." (PMID 29463565, 2018). "Targetable FGFR3 mutations are only frequent enough in urothelial and bladder carcinoma for our analysis." (PMID 30442178, 2018). "FGFR3 alterations (mutations or translocation) are among the most frequent genetic events in bladder carcinoma." (PMID 29463565, 2018). "FGFR3 alterations (mutations or translocations) are among the most frequent genetic events in bladder carcinoma." (PMID 29463565, 2018). "The most established link between FGFRs and cancer is probably with bladder cancer, in which FGFR3 is one of the most commonly mutated genes and the mutations are associated with a non-invasive behavior." (PMID 29159601, 2018). "Alterations of FGFR3 (mutations or translocation) are among the most frequent genetic events in bladder carcinoma, occurring in about 70% of NMIBCs and 20% of MIBCs." (PMID 29463565, 2018). "In contrast, a phase I trial of BGJ398 showed anti‐tumour activity in FGFR3‐mutated advanced bladder cancer after failure of platinum‐based chemotherapy." (PMID 30043421, 2018). "We investigated the molecular mechanisms underlying the oncogenic activity of aberrantly activated FGFR3 in bladder carcinomas, by studying the MGH‐U3 and RT112 cell lines." (PMID 29463565, 2018). "It is also well known that the constantly activated FGFR3 by point mutation can stimulate cell proliferation and plays an oncogenic role in bladder cancer." (PMID 28655970, 2017). "This study provided some insights on the mechanism underlying the carcinogenesis of FGFR3 in bladder cancer." (PMID 28320388, 2017). "There are reports describing that it is possible to target FGFR3, and specifically the S249C variant, e.g. in bladder cancer cell lines, opening an option for more personalized treatment in the future." (PMID 28525363, 2017). "Previous study revealed that FGFR3 is linked to the development of bladder cancer and FGFR3 overexpression and mutations are frequent events in patients with bladder cancer." (PMID 28320388, 2017). "FGFR3 mutations are particulary frequent in bladder cancer, where they are associated with low grade, early stage, and better survival." (PMID 27844328, 2017). "Cox regression model was applied to identify the potential genes in the FGFR3-centered PPI network that were associated with bladder cancer prognosis." (PMID 28320388, 2017). "Of the 94 enrolled patients initially, partial responses were seen in 4 FGFR3 mutated bladder cancers, 2 FGFR1 amplified SqCLC, and a reduction in tumor burden was seen in FGFR2 fusion cholangiocarcinoma as well as in FGFR1 amplified breast cancer." (PMID 28030802, 2017).
bladder cancer (continued). "Protein–protein interaction (PPI) and regulatory networks related to FGFR3 were constructed to investigate the possible mechanisms underlying the oncogenic role of FGFR3 in bladder cancer." (PMID 28320388, 2017). "Fibroblast growth factor receptor 3 (FGFR3) has been shown to be a druggable target in bladder cancer, with its activating mutation being associated with recurrence." (PMID 28388658, 2017). "The same analyses also revealed that FGF-2 correlates negatively with the expression, mutation and copy number variations of FGFR-3, all of which are associated with noninvasive bladder carcinomas." (PMID 28515962, 2017). "Mutations in FGFR3 were associated with decreased estimates of multiple immune infiltrate types in bladder cancer and increased NK cell estimates in head and neck cancer." (PMID 28749946, 2017). "Aberrant activation of FGFR3 by overexpression of activation mutation is common in bladder cancer and it has been shown to modulate lipid metabolism in order to maintain tumor growth and survival." (PMID 28388658, 2017). "FGFR3 has previously been reported to be mutated in HPV+ HNSCC and the common specific variant of FGFR3, S249C, is a putative treatment target in urinary bladder cancer." (PMID 28525363, 2017). "FGFR3 (fibroblast growth factor receptor 3), a receptor tyrosine kinase, is one of the most frequently mutated genes in bladder cancer." (PMID 26924873, 2016). "Two of the most frequently mutated genes in bladder cancer with point-mutation hotspots are FGFR3 and TERT." (PMID 26901314, 2016). "We assessed the performance of associating a FGFR3 mutation assay and a DNA methylation analysis to improve bladder cancer detection and to predict disease recurrence of NMIBC patients." (PMID 27586786, 2016). "Even though FGFR3 mutation was rare in this cohort, we analyzed the recurrence-free survival as a clinical indicator that is known being associated with FGFR3 mutation in bladder cancer." (PMID 27669755, 2016). "In UC, pathway activation results primarily from point mutated FGFR3, which is particularly frequent in low grade non-invasive bladder cancers." (PMID 27669755, 2016). "Mutations of the FGFR3 gene are one of the most frequent genetic alterations in bladder cancer and have been shown to be associated with tumors with a favorable prognosis." (PMID 27154171, 2016). "Bladder cancer with mutation of the RB1 gene exhibits low FGFR3 levels and is associated with significantly poor disease-specific survival." (PMID 26924873, 2016). "Activating mutations, gene fusion and overexpression of FGFR3 in bladder cancer have been documented, indicating that bladder cancer is a promising indication for the discovery of novel FGFR inhibitors." (PMID 27029060, 2016). "FGFR3 has been reported to be associated with several conditions, including achondroplasia, thanatophoric dwarfism and bladder cancer." (PMID 26914935, 2016). "The most common mechanism leading to FGFR3 activation in bladder cancer is activating point mutation of the gene." (PMID 27669755, 2016).
bladder cancer (continued). "Another uncommon cancer-type specific partition of mutations can be seen in the case of FGFR3, where both extracellular regions are linked exclusively to bladder cancer while the intracellular regions are present in various forms of skin tumors as well." (PMID 27150584, 2016). "Fibroblast growth factor receptor 3 (FGFR3) currently appears to be the most frequently mutated oncogene in bladder cancer and implies a good prognosis." (PMID 27999595, 2016). "A distinct pattern of cancer mutations in FGFR1-4 can reflect differences in cancer types and their etiology, with FGFR3 mutations being most prevalent in a single cancer type (i.e bladder cancer)." (PMID 26992226, 2016). "The herein used FGFR inhibitors TKI258 and BGJ398 are already applied in clinical trials of other tumor entities, such as FGFR3 mutated bladder cancer or squamous cell lung cancer with FGFR1 amplification (e.g. NCT01004224 or NCT01831726)." (PMID 26036639, 2015). "For instance, some cases of bladder cancer harbor the mutated FGFR3 gene, leading to the ligand-independent dimerization or enhanced kinase activity of FGFR3." (PMID 26318045, 2015). "In human bladder cancer, the FGFR-3 mutations were observed to be strongly associated with non invasive, low grade and stage." (PMID 26465941, 2015). "Previous studies found that FGFR3 gene mutations were associated with many epithelial malignancies, including cervical carcinoma, nasopharyngeal carcinoma, colorectal cancer and bladder cancer." (PMID 26431494, 2015). "For instance, mutations in FGFR3 are frequent in bladder carcinoma, and FGFR2 mutations in endometrial cancer, melanoma, and gastric tumors." (PMID 26224133, 2015). "In MM, the specific role of ectopically expressed FGFR3 in a subset of cases remains controversial, while in bladder cancer, FGFR3 has been recently implicated as an important driver of proliferation." (PMID 24466111, 2014). "FGFR3 mutations are found in >70% of low-grade, noninvasive bladder cancers and in 15–20% of high-grade tumors." (PMID 24944696, 2014). "In a second study, FGFR3 staining of a tissue microarray comprising 257 pTa and pT1 bladder cancer samples revealed a significant association between FGFR3 overexpression and well-differentiated, early stage tumors." (PMID 24944696, 2014). "These allowed us to focus on interesting aspects and identify mechanisms potentially underlying the different responses of bladder cancer cells to different growth factor receptors (EGFR versus FGFR3)." (PMID 24250280, 2013). "This is coherent with the contention that FGFR3 mutations, mainly characterising non-invasive bladder carcinomas, relatively mildly induce proliferation due to the action of ERK cascade." (PMID 24250280, 2013). "As we build our model around the comparison between EGFR over-expression and FGFR3 activating mutation in bladder cancer, our first simulations were dedicated to the assessment of the model behaviour in these circumstances." (PMID 24250280, 2013). "Ten of 11 samples examined (4 grade 1 and 7 grade 1–2) had mutations in FGFR3: 1 had R248C, 8 had S249C, and 1 had Y373C, consistent with previous studies of early stage bladder cancer." (PMID 23593348, 2013). "We describe a case in which the urine based CertNDxTM Bladder Cancer Assay, for mutations in FGFR3, played a pivotal role in diagnosing urothelial cancer in the urinary tract of a patient." (PMID 22873290, 2012). "In a recent bladder cancer study FGFR3 mutation in combination with APC, RASSF1A, and SFRP2 methylation markers provided a sensitivity of 90% using tissue samples and 62% using paired urine samples to identify the presence of cancer with 100% specificity." (PMID 22530128, 2012).